CIITA (class II major histocompatibility complex transactivator)
Diseases named in the same sentence as CIITA in open-access papers (continued):
Sharing a sentence is not in itself a finding about the gene and the disease.
tumor (continued). "Utilizing multivariate Cox regression analysis, we developed a prognostic nomogram for estimating overall survival by integrating key clinicopathological variables: tumor stage, PAM50 subtype, age at diagnosis, and CIITA expression status." (PMID 40861816, 2025). "Given its selective expression pattern in tumor cells, RCOR2 is a specific corepressor of CIITA and MHC-II in tumor cells." (PMID 40608411, 2025). "Controlled and forced expression of CIITA in MHC class II-negative hepatocellular cell lines rendered them MHC class II-positive and allowed for better recognition of tumor antigens by CD4+ helper T cells." (PMID 40141198, 2025). "In these models, CIITA‐transfected/infected MHC‐II‐positive cells were found to activate CD4+ T‐cells, resulting in tumor rejection or growth retardation in mice with subcutaneous tumors." (PMID 39535369, 2025). "However, analysis of single‐cell RNA‐sequencing (RNA‐seq) of GB patient tumors revealed that tumor cells do not express CIITA nor genes encoding for MHC‐II antigen processing (CD74, HLA‐DMA, HLA‐DOA) and presentation (HLA‐DQA1, HLA‐DQB1, HLA‐DRA, HLA‐DRB1, HLA‐DRB5)." (PMID 39535369, 2025). "Simultaneously, RCOR2 inhibited CIITA expression through HDAC1/2-mediated deacetylation of histone H4 at lysine 16, leading to MHC-II silencing in tumor cells and subsequent impairment of CD4+CD8+ T cell immunosurveillance, thereby promoting immune evasion." (PMID 40608411, 2025). "Firstly, we find that a novel CIITA mutant, unable to induce MHC‐II still triggers T‐cell‐mediated tumor cell death." (PMID 39535369, 2025). "Disruption of the BAP1/IRF1/CIITA axis leads to a functional attenuation of MHC-II expression and MHC-II–dependent immune cell infiltration, leading to accelerated tumor growth in immunocompetent mice." (PMID 39817454, 2025). "In this regard, viral vectors containing CIITA can be optimized to vehicle the MHC class II transactivator directly and specifically into OSCC tumor mass, as this tumor is easily accessible for direct injection." (PMID 39035008, 2024). "The rational was to render tumor cells MHC-II-positive by genetic transfer of CIITA and then assess the in vivo behavior of CIITA-tumor cells." (PMID 39035008, 2024). "Consistent with our previous study, significant high infiltration of pDCs was found in the tumor-bearing brain (tumor vs. normal: 35.4% vs. 9.4%, p < 0.05), and nearly 100% of them (98.5%) were MHC-II and CIITA double-positive." (PMID 39456552, 2024). "Epigenetic regulation of CIITA is also an important element in the expression of this protein and has a major impact on MHC-II expression in tumor cells possibly facilitating immune escape." (PMID 37467968, 2023). "In this paper, we further investigate the extent of protection truly conferred by CIITA in GB cells in the C57BL/6 mice model and assess its effects in co-cultures of (syngeneic primary) human GB cells and tumor-infiltrating human immune cells." (PMID 38201622, 2023). "CGP of PCL tissues revealed the tumor to be wildtype for CD79B, MYD88, CARD11, and TNFAIP3, with genomic alterations detected in SMO, CIITA, ETS1, HST1H1D, and SOCS1." (PMID 36342081, 2023). "Four devils (My, TD4, TD5 and TD6) that developed DFT1 tumours and subsequent serum antibodies (immune) that bound MHC-I were selected for screening against CIITA-expressing DFT1 and DFT2 cells." (PMID 36259237, 2022). "Several studies in murine models have demonstrated immune-mediated tumour rejection and/or tumour growth retardation using MHC-II-expressing tumour cell lines, either through CIITA or MHC-II gene transfer." (PMID 36259237, 2022). "The gene expression of CIITA can be regulated at the post-transcriptional level by miRNAs, and both tumor cells and the tumor ECM trigger the upregulation of miR-146b-5p and let-7i-5p, which target the mRNA for CIITA." (PMID 34680345, 2021).
tumor (continued). "MHC class II transactivator (CIITA), is a recurrent gene fusion partner for 9p.24 translocations in PMBCL which further reduced tumor immunogenicity through decreased antigen presentation and these translocations are associated with poorer outcomes." (PMID 34068762, 2021). "For instance, HDAC2 degrades CIITA to antagonize its activity and promotes the expression of MHC-II, highlighting its important role in the anti-tumor reactivity." (PMID 34365463, 2021). "Not only are 16p13 abnormalities a novel association in dFL, we also found that the minimally altered region(s) encompassed CREBBP, CIITA, and SOCS1, which suggests a possible co-operative mechanism for tumor immune evasion." (PMID 32555149, 2020). "Additionally, our approach unveiled a noticeable exception to the dogma that dendritic cells are the sole professional antigen presenting cells (APC) capable to prime naïve TH cells, because CIITA-dependent MHC-II expressing tumor cells could also perform this function." (PMID 31417570, 2019). "Two highly tumorigenic MHC-II-negative C57BL/6 H-2b tumor cell lines, MC38 colon carcinoma and LLC Lewis lung carcinoma, were stably transfected with CIITA and selected for expression of MHC class II molecules." (PMID 31417570, 2019). "In response to OV infection, type I and II IFN secretion by infected cells within the tumor environment (which also includes normal tumor infiltrating cells) leads to the up-regulation of hundreds of ISGs including IRF-1, which up-regulates CIITA expression." (PMID 24062768, 2013). "Moreover, the fact that CIITA-transfected tumor cells could trigger a potent anamnestic and persistent anti-tumor T cell response without an apparent sequel of autoimmunity, suggests that most of the anti-tumor response was directed against tumor- and not self-derived antigens." (PMID 22849661, 2012). "Since it is known that a broad spectrum of tumor cells lack MHC presentation and show hypermethylation of IFNγ target genes such as CIITA, we treated RMS cells with the demethylation reagent 5′aza 2′deoxycytidine." (PMID 22919516, 2012). "Intriguingly, both wild‐type and mutant Ad‐CIITA, but not unarmed AdV, triggered immune‐mediated tumor cell death in the co‐culture system, suggesting an at least partially MHC‐II‐independent process." (PMID 39535369, 2025). "Intriguingly, we have detected a significant reduction of tumor growth in the absence of CIITA/MHC-II expression in an animal model." (PMID 39817454, 2025). "In GB organoid–immune cell co‐culture systems, Ad‐CIITA induces immune‐mediated disruption of the organoids and tumor cell death, independent of MHC‐II expression." (PMID 39535369, 2025). "CIITA KO counteracted RCOR2 KO1–induced MHC-II molecules in TUBO and MC38 cells, suggesting that RCOR2 indirectly reduces MHC-II expression in tumor cells by repressing CIITA." (PMID 40608411, 2025). "Key transcription factors (TFs), such as CREB1, CIITA, and ICAM1, regulate the expression of immune-related genes, including those involved in antigen processing and HLA class I/II expression, thereby influencing tumor antigen presentation." (PMID 41312385, 2025). "Preliminary experiments indicated an increase in the CD8/CD4 ratio and a two-fold increase in the expansion capacity of CAR-T cells without tumor stimulation when B2M and CIITA were knocked down." (PMID 39856752, 2025). "Tumours with early WGD had significantly lower expression of CIITA compared to those with late or no WGD (p = 0.04, Kruskal-Wallis test, ICGC dataset)." (PMID 39025846, 2024). "We confirmed that CIITA was expressed in proportionally fewer cancer cells within each patient sample in tumours with early WGD, compared to those with late or no WGD (p = 0.04)." (PMID 39025846, 2024). "We analyzed CNV data of paired normal and tumor WES generated using the Sequenza pipeline in the context of the MAPPYACTS study for the chromosome arms 6p (HLA region), 15q and 16p (containing the B2M and CIITA genes, respectively)." (PMID 38318504, 2023).
tumor (continued). "Human GB-infiltrating myeloid cells, lymphocytes and NK cells remained mostly inactivated and/or tumor-supportive when in co-culture with GB cells, regardless of CIITA." (PMID 38201622, 2023). "Interestingly, prior studies showed that ERK signaling negatively regulates constitutive but also IFNγ-induced CIITA expression, suggesting that oncogenic Ras-RAF-MEK-ERK pathway activation in tumor cells counteracts MHC class II antigen presentation." (PMID 37965314, 2023). "Once transformed with CIITA, tumor cells express MHC class II molecules and thus may act as surrogate APCs for their own tumor antigens for optimal presentation to tumor-specific Th cells." (PMID 36993983, 2023). "With CIITA expression and HLA-DM functionality compromised, the transcriptional regulation of MHC class II genes and loading of tumour peptides is hindered, which negatively impacts the efficient display of tumour antigens to T cells." (PMID 37454231, 2023). "Other cells, in this case tumor cells, can efficiently process and present endogenous peptide antigens to naïve Th cells provided they express MHC-II molecules in a “physiological” fashion, that is under the control of CIITA." (PMID 37467968, 2023). "LAMP1 expression in NK cells—a potential marker of anti-tumor activity—was consistently high, independent of CIITA expression in U87 or GM2." (PMID 38201622, 2023). "TAMs expressed more CD163 when co-cultured with tumor cells, regardless of CIITA expression, than when grown in monoculture (p = 0.01)." (PMID 38201622, 2023). "CIITA-based anti-GB treatment can restore antigen presentation on MHC class II molecules at the surface of GB cells, and it is thought to induce an immune-mediated anti-tumor immune response." (PMID 38201622, 2023). "Altogether, the results of our co-cultures of CIITA-expressing human GB cells with different subsets of tumor-infiltrating immune cells do not suggest any major immunomodulatory effect of CIITA on the tumor microenvironment." (PMID 38201622, 2023). "In tumor cells, 284/314 cases lacked CIITA expression, 23/314 expressed low and 1/314 lesions medium levels of CIITA." (PMID 34359808, 2021). "In summary, tumor grading is correlated with CD4+ T-cell infiltration and CIITA expression." (PMID 34359808, 2021). "In contrast, CIITA expression in lymphocytes, but not in tumor cells, correlated to tumor staging (p = 0.0029 and p = 1, respectively)." (PMID 34359808, 2021). "CIITA-driven MHC class II-expressing tumor cells optimally stimulate in vivo tumor specific MHC class II-restricted CD4 T cells generating specific and long lasting protective immunity against the tumor." (PMID 33138029, 2020). "CIITA and RFX5, two important activators of transcription of MHC-II pathway genes that are regulated by IFNγ, are highly upregulated in EBVaGCs and their expression is strongly correlated with IFNG across individual tumor samples." (PMID 32901107, 2020). "Although this enzyme represses CIITA transcription by the K27m3 of histone 3, thereby silencing HLA Class II expression, we observed a high expression of EZH2 in high-risk M3 tumours, without any association to HLA Class I expression." (PMID 33316946, 2020). "A study using gastric and colorectal tumor cell lines demonstrated that a subset of these tumor cells do not induce CIITA expression following IFN-γ stimulation." (PMID 25071778, 2014). "One possible conclusion from these findings was that tumor cells expressing CIITA-dependent MHC-II molecules could serve themselves as APC of their own TAA for initial triggering and priming of tumor-specific TH cells." (PMID 24600588, 2014). "We found that 25 out of the 33 tested inflammasome-related genes were detectable by quantitative RT-PCR, and 8 of them (CIITA, NLRC4, NLRP3, NLRP7, AIM2, RIG-I, ASC and IL-1β) were overexpressed (fold change, >2) in NPC tumour samples, compared to adjacent normal samples." (PMID 23065753, 2012).
tumor (continued). "To explore the cause of the absence of MHC class II molecules in haematopoietic tumour cells, we examined the relationship between expression of HLA-DR and its co-activators (CIITA and RFX complex)." (PMID 14970863, 2004). "The relevance of tumour cells as APC for CD4+ cells appears to be dependent on the coexpression of MHC II and accessory molecules such as the invariant chain (Ii) and HLA-DM, each of which are under the primary control of CIITA, the Class II transactivator." (PMID 12569387, 2003). "Taken together, these results represent the first evidence that a protective adaptive immune response against OSCC, the most frequent tumor of the oral cavity, may be elicited in vivo by inducing the tumor cells to express MHC-II molecules in a CIITA-dependent manner." (PMID 39035008, 2024). "We, however, challenged this paradigm by showing that these results were not reproducible in cell transfer experiments and that CIITA-expressing human GB cells did not elicit any strong activation of tumor-infiltrating lymphocytes in human syngeneic co-cultures." (PMID 39594630, 2024). "Continuous cloning of the CIITA-transfected cells and selection of more stable and highly MHC-II-expressing transfectants can overcome the problem and result in a more efficient rejection in vivo of the modified tumor cells, as we have shown in previous analyses." (PMID 39035008, 2024). "We, however, showed that these effects were not reproducible in adaptive cell transfer experiments and that CIITA overexpression in GB cells failed to significantly alter the activation of syngeneic, tumor-infiltrating immune cells in syngeneic human primary co-culture experiments." (PMID 39594630, 2024). "It remains quite possible that hypermethylation of the pIV promoter of CIITA controls tumour-specific MHC-II expression, however we could not demonstrate this here, due to the limitations of genome-wide methylation arrays used in the included studies." (PMID 39025846, 2024). "However, murine GL261 tumor cells are also known to elicit an immune reaction against subsequent challenges in C57BL/6 mice independent of CIITA transactivation, and additional controls are required prior to drawing such a conclusion." (PMID 38201622, 2023). "Furthermore, we evaluated MHC-II expression in both pre-vaccinated and non-vaccinated mice, confirming its expression by GL261-CIITA tumor cells (pre-vaccinated, tum CIITA)." (PMID 36993983, 2023). "Most tumor cells do not express MHC class II molecules because of a lack of expression of CIITA." (PMID 36993983, 2023). "A combination of in vivo induction of CIITA and characterization of the MHC-II-bound immunopeptidome may be, in the near future, a possible novel approach to treatment of this still therapeutically unresponsive and deadly form of tumor." (PMID 36993983, 2023). "Overall, our study highlights the selectivity of direct presentation of endogenous antigens by MHC-II+ tumor cells and demonstrates that neither CIITA expression nor the presence of a membrane-bound antigen is sufficient alone to promote direct recognition of tumor cells by CD4+ T cells." (PMID 36512410, 2023). "Alternatively, the inability to express MHC-II molecules in CIITA-overexpressing DFT2 cells might be due to epigenetic or post-transcriptional regulation, possibly as a consequence of the differentiation state of DFT2 tumours compared to DFT1." (PMID 36259237, 2022). "It will be interesting to assess the general validity of this approach and determine whether professional APCs and CIITA-transformed non-APCs, such as tumor cells, use the same basic machinery to process endogenous peptides." (PMID 33592498, 2021). "The expression of MHC class II molecules driven by CIITA was an obligatory requirement to induce the anamnestic protective response against the parental tumor, and this received confirmation also by experiments using as a vaccine non-replicating CIITA-transfected tumor cells." (PMID 31417570, 2019).
tumor (continued). "Nevertheless, they did not formally prove that CIITA-tumor cell could function as classical APC in triggering the priming of naïve tumor antigen-specific TH cells." (PMID 31417570, 2019). "Furthermore, it was shown that CIITA-tumor vaccinated mice develop an anamnestic response not only against the CIITA-transfected tumor but, most importantly, against the parental tumor leading to a very efficient rejection of the parental tumor as well." (PMID 31417570, 2019). "CIITA-dependent MHC class II expression in tumor cells was instrumental to trigger the anamnestic protective immune response against the parental tumor, as also demonstrated by vaccination experiments with non-replicating CIITA-transfected tumor cells." (PMID 24600588, 2014). "Interestingly, mice rejecting CIITA-tumors and mice vaccinated with CIITA-tumor cells rejecting a challenge with parental tumors displayed a polarized CD4+ TH1 cell phenotype in their tumor-draining lymph nodes, as compared to TH2-like cells found in parental tumor-bearing mice." (PMID 22849661, 2012). "Whether CIITA-driven MHC class II expressing tumor cells may also spontaneously acquire or be endowed in part with phagocytotic function and thus eat the other dead tumor cells and cross-present their tumor antigen to the naïve lymphocytes just like human immature DCs, remains to be investigated." (PMID 31417570, 2019). "The transactivator protein CIITA plays an essential role in the transcriptional regulation of MHC class II genes and non-MHC genes, including CD7441, 42, and its significant reduction in tumour-induced DCs might explain the decreased expression of antigen-presenting genes." (PMID 28350008, 2017). "Furthermore, it was shown that mice vaccinated with CIITA-transfected tumor cells develop an anamnestic response not only against the CIITA-expressing tumor but also, most importantly, against the CIITA-negative parental tumor cells leading to a very efficient rejection of the parental tumor." (PMID 24600588, 2014). "Most tumor cells, both carcinoma and sarcomas, do not express MHC-II molecules because of lack of expression of CIITA." (PMID 37467968, 2023). "IFN-γ can induce the expression of more than 200 genes, including those involved in immune evasion by tumor cells, such as PD-L1, PD-L2, CTLA-4, CIITA, non-classical MHC class Ib antigens, IDO1, and CXCL12." (PMID 37444608, 2023). "We found that MC38 and LLC tumor cells do not express CD80 and CD86 costimulatory molecules and this phenotype is not modified by CIITA expression." (PMID 31417570, 2019). "Unlike Ad‐CIITA, Ad‐GFP did not lead to tumor cell death upon co‐culture with PBMCs." (PMID 39535369, 2025). "Allogeneic anti-CD19 CAR T cells triple-knockout for HLA class I (β2-microglobulin KO), class II (CIITA KO) and TCR (α-chain KO) showed better persistence than double-knockout (β2-microglobulin and TCR) cells in a mouse tumor model, with anti-tumor activity, but without GVHD." (PMID 33746981, 2021). "Furthermore we have previously found that inducing expression of CIITA in PELs, which consequently upregulates surface class II expression, allows recognition by KSHV-specific CD4+ T cells but not killing of these tumor cells." (PMID 27893813, 2016). "Murine tumour cell lines could be divided into three groups: constitutive MHC class II and CIITA expression; inducible MHC class II and CIITA expression upon IFN-γ-treatment; and lack of constitutive and IFN-γ-inducible MHC class II and CIITA expression." (PMID 11027433, 2000). "To determine whether this mechanism may be preventing recognition of MHC-II+ tumor cells by CD4+ T cells, we cultured CD4+ T cells expressing our KRASG12V-specific TCR or the E6-specific F12 TCR with NCI-H2444 CIITA and HNSCC-56 CIITA, respectively, with or without anti–PD-L1–blocking Abs." (PMID 36512410, 2023).